PRDX6 (peroxiredoxin 6)
Diseases named in the same sentence as PRDX6 in open-access papers (continued):
Sharing a sentence is not in itself a finding about the gene and the disease.
sarcopenia (5 papers, 2019 to 2024). Progressive decline in muscle mass due to aging which results in decreased functional capacity of muscles. "Particularly, peroxiredoxin 6 (Prdx6) has been demonstrated to regulate both myogenesis and adipogenesis via the control of glucose uptake, and Prdx6−/− mice display increased levels of markers of senescence, metabolic sarcopenia, and loss of muscle strength." (PMID 34560818, 2021). "As expected, the levels of ubiquitinated proteins were higher in Prdx6-/- (p < 0.05), suggesting that even the mechanism of muscle atrophy is implicated in Prdx6-associated sarcopenia." (PMID 32316601, 2020). "Our results instead indicated a metabolic sarcopenia, which may be associated to a cellular specific increase in oxidative stress linked with the loss of Prdx6." (PMID 32316601, 2020). "Together, our results suggest that Prdx6 may be proposed as a novel biomarker and pharmacological therapeutic target to prevent and cure metabolic diseases and sarcopenia associated with accelerated aging." (PMID 32316601, 2020). "The present study, innovatively, highlights a fundamental role of Prdx6, in the crosstalk between aging, sarcopenia, and DM." (PMID 32316601, 2020). "Prdx6 involvement on metabolic sarcopenia is further evident by the increase in muscle atrophy markers in Prdx6-/- mice." (PMID 32316601, 2020). "Strengths of the present study include the use of well-validated knockout mice model and the stably silenced C2C12 murine myoblast cell line for Prdx6 that were innovatively proposed as model to study cellular aging and sarcopenia." (PMID 32316601, 2020). "In this study, we found a reduction in CSA of Prdx6-/- skeletal muscle fibers compared to control group, demonstrating the presence of sarcopenia." (PMID 32316601, 2020). "In order to measure mice muscle strength, as marker of sarcopenia, we performed the grip test on both forelimbs and hindlimbs in wt and Prdx6-/- mice." (PMID 32316601, 2020). "Based on these data and on the previous findings, we aim to evaluate the presence of sarcopenia, as advanced phenotype of cellular aging, in Prdx6-/- mouse model." (PMID 32316601, 2020). "This points to a role for Prdx6 in the maintenance of muscle mass and points to a possible use of this enzyme for therapy in diabetic myopathy and sarcopenia." (PMID 30871234, 2019). "First of all, we established as absence of Prdx6 in mice resulted in a loss of muscle contractile force measured by grip test, which is commonly used to evaluate sarcopenia, either in forelimbs or hindlimbs." (PMID 32316601, 2020). "The insulin release deficit as well as the impaired insulin signaling leading to reduction of muscle glucose uptake present in Prdx6-/- mice, could explain by themselves, at least in part, the role of Prdx6 on sarcopenia." (PMID 32316601, 2020). "However, the use of Prdx6-/- as model of premature cellular aging/sarcopenia may help in this challenge." (PMID 32316601, 2020). "Our study investigated the plasma proteome of individuals with age-related sarcopenia and identified 8 DEPs that showed promising predictive performance, including IGFBP2, PON3, LRG1, PRDX6, PTGDS, CD163, PRG4, and TRAJ17." (PMID 39725826, 2024). "Further confirming this evidence, we demonstrated as lack of Prdx6 induces sarcopenia in mice, affecting both cellular muscle differentiation and muscle atrophy mechanisms." (PMID 32316601, 2020). "In order to confirm the presence of skeletal muscle atrophy in absence of Prdx6, typical of sarcopenia, we compared the histological features of wt and Prdx6-/- gastrocnemius muscles." (PMID 32316601, 2020).
acute kidney injury (4 papers, 2017 to 2026). Sudden and sustained deterioration of the kidney function characterized by decreased glomerular filtration rate, increased serum creatinine or oliguria. "In summary, our results suggest that PRDX6 overexpression attenuates LPS-induced acute kidney injury." (PMID 28881633, 2017). "PRDX6 protects against neuronal death caused by oxidative stress, and can reduce LPS-induced renal ROS concentrations and inactivate the p38 MAPK and JNK pathways, thereby attenuating LPS-induced acute kidney injury." (PMID 37817228, 2023). "Therefore, we investigated the role of PRDX6 during lipopolysaccharide (LPS)-induced acute kidney injury." (PMID 28881633, 2017).
atherosclerosis (4 papers, 2007 to 2021). A disease characterized by the build-up of fatty material and calcium deposition in the arterial wall resulting in partial or complete occlusion of the arterial lumen. "A study tested the relationship between PRDX6 and atherosclerosis using Prdx6−/− with three different genetic backgrounds: atherosclerosis-resistant 129/SvJ, atherosclerosis-susceptible B6, and mixed B6;129." (PMID 32098329, 2020). "The effects of Prdx6 deficiency in atherosclerosis are minor and background dependent." (PMID 32098329, 2020). "Although Prdx6 has been extensively studied, more detailed studies are necessary to elucidate the role of Prdx6 in the pathogenesis of atherosclerosis." (PMID 34439492, 2021). "There have been numerous reports documenting a link between PRDX6 and certain diseases, such as atherosclerosis, sporadic Creutzfeldt–Jacob disease and Pick disease." (PMID 17980029, 2007). "As a possible link between Prdx6 and atherosclerosis Prdx6 possesses PLA2 activity." (PMID 34439492, 2021). "Supporting the hypothesis that PRDX6 may be pivotal in the physiological link between glycemic and lipid components of metabolism, another study, using PRDX6 mice fed with a high-fat diet (HFD), demonstrated that these rodents were more susceptible in developing atherosclerosis compared to controls." (PMID 31949886, 2019).
cataract (4 papers, 2018 to 2026). Partial or complete opacity of the crystalline lens of one or both eyes that decreases visual acuity and eventually results in blindness. "This leads to over-modulation of the expression of certain genes, such as LEDGF, Prdx6, αSMA, Tpm, and βig-h3, changes in which have been implicated in the induction of cataracts, ASF and PCO as well as other EMT-related disorders." (PMID 30304871, 2018). "Thus, in this work, to postpone or treat cataracts, which is one of the huge problems of blinding disorders, we intended to enhance further the stability and activity of WT-Prdx6 or Sumoylation-deficient Prdx6." (PMID 34439493, 2021). "Overall, we conclude that enhancing Prdx6 activity offers a promising strategy to prevent or reverse age-related cataracts." (PMID 41577330, 2026). "Previously, we reported that the subconjunctival delivery of Prdx6-linked to TAT (Transcriptional Activator of Transcription) transduction domain protected lens cells and delayed cataract formation in Shumiya cataract rats." (PMID 34439493, 2021). "Additionally, lutein and water chestnut extract reduced the lens opacity in rats with cataracts and increased peroxiredoxin 6 and catalase expression both in rats with cataracts and human lens epithelial cells." (PMID 39334773, 2024). "In our previous studies, the expression of Prdx6 was reduced and the expression of TGF β1 and aSMA was markedly up-regulated in cataractous lenses from Shumiya cataract rats." (PMID 30304871, 2018). "Considering the wide range of protective and survival activities of Prdx6, we chose to use the SCR (a model for cataract), which shows a spectrum of biochemical and morphological changes, including oxidative-induced cell biological changes during the progression of cataract." (PMID 34439493, 2021).
dementia (4 papers, 2015 to 2025). Loss of intellectual abilities interfering with an individual's social and occupational functions. "Furthermore, additional proteins which were consistently altered in both the FLNC-, GRN- and VCP-unique datasets, e.g. GFAP, NPTN, DBI, PRDX6, MARCKS and BSN, are closely associated with cognitive function, dementia and pathological aging." (PMID 26555887, 2015). "PRDX6 was only expressed in astrocytes of mouse brain among the six mammalian PRDXs (PRDX1 - 6), and it also was reported to be elevated in reactive astrocytes of human PD patients and dementia patient brains, and implying unique roles of PRDX6 in astrocytes." (PMID 26327204, 2015).
endometrial cancer (4 papers, 2019 to 2025). Primary or metastatic malignant neoplasm involving the endometrium (mucous membrane that lines the endometrial cavity). "For plasma proteins, a 4-marker panel combining CNDP1, CDC5L, APOD and PRDX6 had the least AIC value and predicted early-stage endometrial cancer with an AUC of 0.88 (0.82–0.95)." (PMID 38513301, 2024).
esophageal squamous cell carcinoma (4 papers, 2010 to 2024). Esophageal squamous cell carcinoma (ESCC) is a type of esophageal carcinoma (EC) that can affect any part of the esophagus, but is usually located in the upper or middle third. "However, another study showed the up-regulation of PRDX6 in metastatic cells and, moreover, PRDX6 was found to be up-regulated in sera of many patients with esophageal squamous cell carcinoma." (PMID 20860785, 2010).
experimental autoimmune encephalomyelitis (4 papers, 2015 to 2025). An autoimmune demyelinating disease of the central nervous system that is produced experimentally in animals by the injection of homogenized brain or spinal cord in Freund's adjuvant. "Moreover, increased PRDX6 expression in experimental autoimmune encephalomyelitis (EAE) mice led to reduced myelin loss, decreased MMP9 levels, and dampened microglial activation, thereby preserving BBB integrity and limiting immune cell infiltration." (PMID 40918143, 2025). "In this study, we showed that the expression of an antioxidant protein peroxiredoxin 6 (PRDX6) is markedly increased in spinal cord of mice with experimental autoimmune encephalomyelitis (EAE) compared to other PRDXs." (PMID 26327204, 2015). "Evidence from experimental autoimmune encephalomyelitis (EAE) mice and MS patients showed increased expression of Prdx6 in the astrocytes of the spinal cord in comparison with the control group, respectively." (PMID 38671897, 2024). "In experimental autoimmune encephalomyelitis (EAE) mice and multiple sclerosis (MS) patients, the expression of Prdx6 is markedly increased in spinal cord astrocytes, which may be related to high levels of nitric oxide (NO) and superoxide after EAE and MS." (PMID 38671897, 2024).
Hyperglycemia (4 papers, 2013 to 2020). An increased concentration of glucose in the blood. "An intensive study shows that Prdx6−/− develop insulin resistance, diabetic dyslipidemia, impaired insulin signaling, morphological changes in the pancreas and liver, and increased pro-inflammatory responses, suggesting that Prdx6 deficiency is a key mediator of hyperglycemia in type 2 diabetes." (PMID 32098329, 2020). "AR upregulation in diabetic cataracts induces apoptosis, demonstrating the therapeutic potential of Prdx6 as an antioxidant in the prevention and control of hyperglycemia-induced complications." (PMID 27242920, 2016). "Intriguingly, in Peroxiredoxin 6 knockout (Prdx6-/-) mice model, we previously reported as the absence of Prdx6, induces a phenotype similar to early-stage of T2DM caused by both reduced glucose-stimulated insulin secretion and increased skeletal muscle insulin resistance with mild hyperglycemia." (PMID 32316601, 2020).
Insulin resistance (4 papers, 2019 to 2022). Increased resistance towards insulin, that is, diminished effectiveness of insulin in reducing blood glucose levels. "In a previous in vivo study, by using Prdx6-/- mice, we demonstrated that lack in Prdx6 resulted in insulin resistance and reduced GSIS." (PMID 35370943, 2022). "We found that PRDX6−/− mice have higher levels of insulin resistance, and PRDX6 protein and mRNA expression decreased in the liver of a mouse model of ethanol consumption." (PMID 31949886, 2019). "Moreover, PRDX6 has been shown to maintain mitochondria integrity under oxidative stress and protect against insulin resistance and non-alcoholic fatty liver disease induced by a high-fat diet." (PMID 34063343, 2021). "Mice lacking PRDX6 but fed with SCD develop a mild form of DM, mainly linked to higher levels of insulin resistance associated with a defect of glucose-stimulated insulin secretion (GSIS)." (PMID 31949886, 2019).
lymph node metastasis (4 papers, 2016 to 2025). "A correlation between the presence of lymph node metastasis and low PRDX6 levels was also described." (PMID 27206673, 2016). "In addition, overexpression of PRDX6 was reported to be significantly correlated with the presence of lymph node metastasis in breast cancer." (PMID 28225015, 2017). "In all stages of lymph node metastasis, the mRNA expression of PRDX2, PRDX4, and PRDX6 was higher in LUAD samples than in normal samples." (PMID 40303499, 2025).
male infertility (4 papers, 2017 to 2025). The inability of the male to effect fertilization of an ovum after a specified period of unprotected intercourse. "PRDX6 has also been shown to underlie the effects of several chemical stressors on male infertility." (PMID 40298631, 2025). "For instance, PRDX6 has been implicated in neurodegeneration, male infertility, and senescence and cancer by attenuating oxidative stress and inflammation." (PMID 40298631, 2025). "Prdx6−/− male mice are subfertile, and the deficiency or inactivation of Peroxiredoxins (PRDXs) is associated with human male infertility." (PMID 29021631, 2017). "A recent systematic review demonstrated that many sperm proteins associated with male infertility—particularly those involved in oxidative stress regulation and mitochondrial function (e.g., PRDX6, SOD1, AKAP4)—are not detected by routine semen analysis." (PMID 41011106, 2025). "Although the precise molecular mechanisms underlying these observations remain largely elusive, these findings have established a strong link between PRDX6 dysregulation and male reproductive health, indicating the critical role of this antioxidant enzyme in the pathogenesis of male infertility." (PMID 40298631, 2025). "We observed similar damages in mouse lacking PRDX6, a condition that generates an in vivo oxidative stress and is associated with male infertility." (PMID 32093059, 2020).
schizophrenia (4 papers, 2009 to 2024). A major psychotic disorder characterized by abnormalities in the perception or expression of reality. "Peroxiredoxin 6 (Prdx6) is an enzyme encoded by the PRDX6 gene, which was a DEG detected in the bipolar disorder, schizophrenia and major depression datasets." (PMID 39727940, 2024). "Both of these PRDX6 activities may be related to schizophrenia pathogenesis since an enhancement of phospholipid turnover has been previously reported in schizophrenia frontal lobe." (PMID 26973466, 2016). "Bipolar disorder, schizophrenia and major depression shared two DEGs: PRDX6 (Peroxiredoxin 6) and GHRHR (Growth-hormone-releasing hormone receptor)." (PMID 39727940, 2024). "Therefore, PRDX6 could function as a brain marker for schizophrenia." (PMID 26973466, 2016). "Besides, the differential expression of peroxiredoxin 6 (PRDX6) and glial fibrillary acidic protein (GFAP) were confirmed by western blot in schizophrenia prefrontal cortex." (PMID 19405953, 2009).
varicocele (4 papers, 2013 to 2025). A condition characterized by the dilated tortuous veins of the spermatic cord with a marked left-sided predominance. "Differential amounts of peroxiredoxin 6 have been reported (41% in men with varicocele and 65% in men with idiopathic infertility)." (PMID 23688036, 2013). "Reduced levels of PRDX6 have also been reported in the seminal plasma from men with varicocele." (PMID 23688036, 2013).
acute lung injury (3 papers, 2011 to 2023). A condition of lung damage that is characterized by bilateral pulmonary infiltrates (pulmonary edema) rich in neutrophils, and in the absence of clinical heart failure. "Little is known about genetic variation within the PRDX6 gene and its association with acute lung injury (ALI)." (PMID 21627785, 2011).
asthma (3 papers, 2012 to 2024). "Oxidative stress can promote asthma by decreasing the level of PRDX6 and changing its activities." (PMID 36611974, 2023). "In general, current studies show that PRDX6 can protect against asthma." (PMID 36611974, 2023). "The results showed that compared with healthy people, the level of PRDX6 in patients with asthma was lower, the peroxidation form of PRDX6 (PRDX6-SO3H) was increased, and the ratio of PRDX6-SO3H/PRDX6 reflected the severity of asthma." (PMID 36611974, 2023). "We also detected decreased expression of PRDX6 and increased expression of ANXA5 in the acupuncture-treated model; however, these two proteins did not exhibit altered expression in asthma onset in rats when compared with the controls." (PMID 23304218, 2012).
diabetic nephropathy (3 papers, 2023). "The specificity protein 1 (Sp1)-mediated upregulation of peroxiredoxin 6 (Prdx6) expression in vitro has been found to prevent podocyte injury in diabetic nephropathy by reducing oxidative stress and ferroptosis." (PMID 38076182, 2023). "Sp1 mediates the upregulation of Prdx6 expression to prevent diabetic nephropathy by alleviating oxidative stress and ferritin deposition, thereby preventing podocyte damage." (PMID 37113991, 2023).
diabetic neuropathy (3 papers, 2022 to 2025). A chronic, pathological complication associated with diabetes mellitus, where nerve damages are incurred due to diabetic microvascular injury involving small blood vessels that supply these nerves, resulting in peripheral and/or autonomic nerve dysfunction. "The mapping results identified peroxiredoxin-6 (PRDX6) as a novel target in diabetic neuropathy, whose biological mechanism was associated with S-palmitoylation." (PMID 36120430, 2022). "The results highlight a central role for PRDX6 palmitoylation in protection against diabetic neuropathy." (PMID 36120430, 2022). "For instance, S-palmitoylation of peroxiredoxin-6, an antioxidant enzyme, enhances its interaction with anion exchanger 3 and activates the Cl−/HCO3− flux inducing pain in diabetic neuropathy." (PMID 38894876, 2024). "Peroxiredoxin-6 (PRDX6) and PEX11B palmitoylation can affect diabetic neuropathy." (PMID 40959086, 2025).
endothelial dysfunction (3 papers, 2019 to 2025). In vascular diseases, endothelial dysfunction is a systemic pathological state of the endothelium (the inner lining of blood vessels) and can be broadly defined as an imbalance between vasodilating and vasoconstricting substances produced by (or acting on) the endothelium. "The overexpression of Prdx6 in ECs prevents AngII-induced inflammation, OS, and endothelial dysfunction via inactivation of the p38 MAPK and c-Jun N-terminal kinase pathways." (PMID 34439492, 2021). "In addition, a significant increase in plasma levels of Prdx6 has been positively correlated with endothelial dysfunction in diabetic patients with PAD." (PMID 34439492, 2021).